INS (insulin)
Diseases named in the same sentence as INS in open-access papers (continued):
Sharing a sentence is not in itself a finding about the gene and the disease.
liver cancer (continued). "To figure out the underlying mechanism of KD affecting liver cancer cell growth, we measured insulin secretion by ELISA in pancreatic β cells cultured in the BHB-Glow medium KD and found that insulin content was significantly decreased in the ketogenic group versus control group." (PMID 39344752, 2024). "However, regional differences were discovered, such as the stronger association between insulin use and liver cancer risk in populations from the Western regions." (PMID 37481610, 2023). "Compared with observation, meta-analysis of the direct comparisons showed that the use of metformin (RR 0.49, 95% CI 0.25–0.97) was associated with a significant risk reduction of HCC, while insulin (RR 2.44, 95% CI 1.10–5.56) appeared to increase the risk of liver cancer." (PMID 27642100, 2016). "Finally, increased physical activity may improve circulation, immune function, energy balance, and insulin sensitivity, which influence and can reduce the associated risks of liver cancer." (PMID 33271947, 2020). "Specifically, it was a metabolic regulation at the systemic level, in which the BHB-Glow medium hindered FOXC2 expression by interfering with glycolytic metabolism and inhibiting insulin production, thereby inhibiting liver cancer cells’ malignant progression." (PMID 39344752, 2024). "To investigate how BHB-Glow medium affected liver cancer cells, we added 10 nM insulin to Huh-7 cells under ketogenic treatment." (PMID 39344752, 2024). "To figure out the influence of insulin secretion on liver cancer cells, we treated liver cancer cells by adding 10 nM insulin to the medium." (PMID 39344752, 2024). "In liver cancer, KD hindered the expression of FOXC2 by reducing insulin production, thereby repressing the proliferation and migration of liver cancer cells in vitro." (PMID 39344752, 2024). "In this study, the BHB-Glow medium simulating KD environment in vitro was found to inhibit insulin production in liver cancer cells." (PMID 39344752, 2024). "The BHB-Glow medium was ascertained by these outcomes to foster the malignant development of liver cancer cells through insulin release from β islet cells." (PMID 39344752, 2024). "We then investigated how insulin affected the malignant behavior of liver cancer cells and found that insulin promoted the proliferation and migration of Huh-7 cells." (PMID 39344752, 2024). "In conclusion, the BHB-Glow medium was able to hinder the expression of FOXC2 by hindering insulin production, thereby suppressing the proliferation and migration of liver cancer cells." (PMID 39344752, 2024). "Together, the medium simulating KD environment strengthened the protection of liver cancer cells by reducing insulin production and down-regulating FOXC2 expression." (PMID 39344752, 2024). "In previous studies, we employed a high concentration of insulin to induce HepG2 cells to establish a stable insulin-resistant cell model (HepG2/IR) and explored the relationship between IR and chemoresistance in liver cancer cells." (PMID 37328795, 2023). "A variety of pathological conditions, such as liver cancer, lead to dysfunction of the insulin signalling pathway in liver cells, which reduces their sensitivity to insulin and leads to IR." (PMID 37328795, 2023). "Previous studies show that the overexpression of TAZ increases insulin signaling in liver cancer and that TAZ deletion in white adipose and muscle increases insulin sensitivity." (PMID 34622775, 2021).
liver cancer (continued). "IRS-1, one of the cytoplasmic adaptor proteins in IRS family, is found in insulin-stimulated Fao liver cancer cells for the first time, which was derived from insulin-stimulated rat liver and 3T3-L1 cells." (PMID 34443299, 2021). "For example, GLUT1 is responsible for regulating glucose transport inside and outside the cells, and it has been found to be upregulated in insulin-resistant liver cancer cells." (PMID 32685545, 2020). "Considering that the human liver is the major organ for metabolism regulated by insulin signals, we employed SK-Hep-1, Huh7, and HepG2 cells derived from liver cancer in this study." (PMID 31212584, 2019). "We identified a set of at least twenty-five (n = 25) genes that play a role either in lipid synthesis and excretion, inflammatory cells recruitment and activation, insulin signaling pathway, or hepatic cancer development." (PMID 31717414, 2019). "Metformin showed higher protective effect of liver cancer when compared with insulin (OR = 0.36; 95% CI, 0.25–0.51), other than sulfonylurea (OR = 0.65; 95% CI, 0.55–0.78) and nonuser of any ADM (OR = 0.62; 95% CI, 0.40–0.98)." (PMID 28489794, 2017). "Propionic acid production has been shown to have beneficial health effects including lowering glucose-induced insulin secretion in isolated pancreatic islet cells of rats and anti-proliferative effects on liver cancer cells." (PMID 29137150, 2017). "DLC1 can be phosphorylated upon expression of AKT or insulin induction in liver cancer cell lines, and S567A mutant (phosphodefective mutant of DLC1) inhibits colony formation in cancer cells and tumor formation in nude mice." (PMID 28903430, 2017). "Insulin, TGs, and ROS can worsen liver function and induce liver inflammation, resulting in development of liver cancer." (PMID 25826083, 2015). "In this study, we attempt to understand the mechanism of insulin in promotion of liver cancer metabolism." (PMID 24895527, 2014). "Those treated with insulin or sulfonylureas monotherapy are more likely to develop colon and liver cancer than those treated with metformin." (PMID 22719752, 2012). "Additionally, we observed a significant decrease in insulin signaling in the liver cancer cell line HepG2 following knockdown of DNAJA2 (SiDJ2), and this effect was consistent when DNAJA2 was knocked out in the mouse syngeneic cancer cell lines 4T1 and MC38." (PMID 41233317, 2025). "Since PNPLA7 expression is downregulated by insulin and insulin signaling is constitutively activated in HCC, excess insulin signaling in liver cancer may lead to downregulation of PNPLA7 expression." (PMID 36979406, 2023). "Indeed, our findings now demonstrate that Trip13 regulates Akt activation, mainly mediated through the IR (a MIM containing protein), with Trip13 being a key player in the p31comet‐/Mad2‐dependent regulation of insulin signaling in liver cancer cells." (PMID 36031387, 2022). "This may be due to the different transient insulin concentrations in collected blood samples from liver cancer patients." (PMID 35740278, 2022). "Meanwhile, STZ could induce significant in vivo growth of xenograft tumors, but treatment with CA or insulin can considerably reduce the size and weight of tumors, suggesting that HG promotes liver cancer cell proliferation but that CA can inhibit it." (PMID 34588426, 2021). "Thiazolidinediones, which lower insulin resistance without directly affecting insulin secretion, also significantly decreased the risk of liver cancer." (PMID 30704150, 2019). "We utilized nationwide population-based cohorts in a HCC-endemic area to determine whether chronic viral hepatitis might signify the role of some insulin analogues in liver cancer oncogenesis." (PMID 31200528, 2019). "Moreover, we identified miRNA-mediated deregulation of several other cancer-related biological processes, including angiogenesis, apoptosis, epidermal growth factor receptor (EGFR)/ErbB signaling, and insulin signaling in gastric, colorectal or liver cancers." (PMID 29459716, 2018).
liver cancer (continued). "Rh-insulin induced cell proliferation of two human liver cancer lines in a dose-dependent manner." (PMID 30477453, 2018). "Regarding site-specific cancers, only the risk of liver cancer was significantly higher in the insulin users compared to that in the non-insulin users (adjusted RR = 2.84, 95% CI 1.12–7.17, P = 0.028)." (PMID 23308218, 2013). "Regarding site-specific cancers, only liver cancer risk was higher in the insulin users compared with the non-insulin users (fully adjusted RR = 2.84, 95% CI 1.12–7.17, P = 0.028)." (PMID 23308218, 2013). "This study confirmed through in vitro cell experiments that KD could inhibit the proliferation and migration of liver cancer cells by targeting down regulation of insulin and FOXC2 expression, providing new theoretical basis for the treatment of liver cancer patients." (PMID 39344752, 2024). "Next, we investigated the influence of ketogenic treatment on the malignant behavior of liver cancer cells, and the proliferation and migration abilities of Huh-7 cells were found weakened after ketogenic treatment, which was reversed by the addition of insulin." (PMID 39344752, 2024). "Estrogen also regulates pathways involved in lipid metabolism and insulin sensitivity, both of which are crucial in the progression of NASH to liver cancer." (PMID 39931368, 2025). "For liver cancer, researchers have noticed that RGN expression was also induced by various hormonal stimulation, including calcitonin, insulin and estrogen." (PMID 37161020, 2023). "Silencing of PRAS40 by small interfering RNA suppresses the mTOR pathway signaling in response to insulin treatment in HEK293 cells, adipocytes, liver cancer cells and ESFT cells." (PMID 28978182, 2017). "In liver cancer cells, E2 or P4 exposure elevated TCF7L2 expression, enhanced the activity of insulin signaling (pAKT/pGSK), reduced PEPCK expression, subsequently increased insulin-stimulated glucose uptake, and decreased glucose production." (PMID 27108846, 2016). "Insulin/proinsulin secretion was measured in MIN6 cells, while glucose uptake and production were evaluated in liver cancer cells." (PMID 27108846, 2016). "Our results contribute to understanding the role of insulin in cancer metabolism and also providing new insights into the role of PKM2 in pathogenesis of liver cancer." (PMID 24895527, 2014). "Contrary to our expectation, p-PDHA1 did not display differential survival for the liver cancer patients analyzed, likely due to alteration of endogenous insulin concentration in patients." (PMID 35740278, 2022). "TAZ has previously been shown to regulate IRS2 expression in liver cancer and to alter insulin sensitivity, but we did not observe effects of TAZ on IRS1/2 expression or insulin sensitivity in mice." (PMID 34622775, 2021). "Hepatic LEPR, whole body IL-6Rα, and combined deficiencies did not alter body composition, insulin sensitivity, and glucose tolerance in the DEN model of liver cancer in vivo." (PMID 30224299, 2018). "Results showed that metformin had higher protective effect of liver cancer when compared with insulin, other than sulfonylurea and nonuser of any ADM." (PMID 28489794, 2017).
liver cancer (continued). "Therefore, we hypothesized that simulating a KD in vitro may lead to a decrease in insulin production and downregulation of FOXC2 expression in liver cancer cells, thereby inhibiting liver cancer cell proliferation and migration." (PMID 39344752, 2024). "The mean (SD) follow-up time for the outcome of liver cancer was 2023.1 (1112.6) days for the GLP-1RA/no insulin group and 2037.9 (766.4) days for the insulin/no GLP-1RA group." (PMID 38967919, 2024). "In liver cancer cells, the insulin/DGUOK‐AS1/miR‐145‐5p axis did not alter the histone acetylation at the SIX1 promoter, suggesting that the insulin/DGUOK‐AS1/miR‐145‐5p axis may not regulate SIX1 expression at the transcriptional level." (PMID 39258807, 2024).
psoriasis (86 papers, 2007 to 2026). An autoimmune condition characterized by red, well-delineated plaques with silvery scales that are usually on the extensor surfaces and scalp. "Specific genetic loci, such as those associated with the interleukin-23 (IL-23)/Th17 axis, are implicated in the pathogenesis of psoriasis and are also involved in metabolic regulation and insulin sensitivity." (PMID 40277935, 2025). "An increasing risk of psoriasis is linked to the frequent use of insulin (adjusted OR: 1.29, 95% CI: 1.18–1.42, p < 0.001)." (PMID 34803716, 2021). "The epidermal changes caused by psoriasis (such as dysdifferentiation and hyperplasia) were consistent with the process of wound healing, so insulin resistance seemed to be an important perspective for studying comorbidities of psoriasis." (PMID 34512732, 2021). "Mechanistically, the presence of common inflammatory pathways, secretion of adipokines, insulin resistance, angiogenesis, oxidative stress, microparticles, and hypercoagulability may explain the association between psoriasis and cardiometabolic disorders." (PMID 29065479, 2017). "Additionally, an improvement to psoriasis has been described when under treatment with pioglitazone, a drug which enhances insulin sensitivity and when there weight-loss improves the response to treatment with cyclosporine for subjects with moderate-severe psoriasis." (PMID 25392783, 2014). "Therapeutic interventions targeting inflammatory pathways have the potential to enhance insulin sensitivity and mitigate cardiovascular risks, underscoring the importance of holistic management strategies for individuals with psoriasis." (PMID 40277935, 2025). "Tumor necrosis factor-α (TNF-α), a key cytokine in the pathogenesis of psoriasis, impairs insulin signaling by inhibiting the tyrosine kinase activity of the insulin receptor and reducing adiponectin secretion." (PMID 40806666, 2025). "The inflammatory milieu in psoriasis can disrupt insulin sensitivity and lipid metabolism, thereby promoting the development of metabolic diseases." (PMID 41432618, 2025). "This is consistent with other studies suggesting that patients with psoriasis are more insulin resistant than healthy controls, which is thought to result from chronic systemic inflammation." (PMID 40584532, 2025). "The patient continued subcutaneous insulin to manage glycemia and received oral anti-silver granules to control psoriasis progression at home." (PMID 37960733, 2023). "The treatment approach included insulin administration to regulate glucose levels, rehydration to correct electrolyte imbalances, and symptomatic treatment of psoriasis with pavoline, anti-silver granules, and narrow-spectrum ultraviolet radiation." (PMID 37960733, 2023). "Chronic inflammation in psoriasis leads to the release of pro-inflammatory cytokines that can interfere with insulin signaling, leading to insulin resistance and impaired glucose metabolism, which are hallmarks of the T2D7." (PMID 37935955, 2023). "The patient ceased treatment with Sintilimab and was initiated on insulin therapy for glycemic control, alongside symptomatic management for psoriasis." (PMID 37960733, 2023). "Of note, unlike previously reported cases, our patient developed isomorphic response under treatment with insulin analogues and during psoriasis flare-up." (PMID 37908249, 2022). "IL-1β blocks insulin-dependent differentiation of keratinocytes and drives keratinocyte proliferation, both of which are hallmarks of psoriasis pathogenesis." (PMID 34816303, 2022). "Of note, treatment with the anti-TNF-α drugs etanercept and adalimumab, commonly used in the treatment of psoriasis, was shown to exert positive effects on insulin sensitivity." (PMID 36012327, 2022). "Insulin sensitivity has been reported to be significantly lower in patients with psoriasis compared to control subjects." (PMID 36589440, 2022).